FAP (fibroblast activation protein alpha)
Diseases named in the same sentence as FAP in open-access papers (continued):
Sharing a sentence is not in itself a finding about the gene and the disease.
tumor (continued). "In this study, our results showed that down-regulation of COL1A1 increased the expression of E-cadherin and Cav-1 in tumor cells and reduced the expression of α-SMA and FAP, thus improving the tumor microenvironment." (PMID 38045487, 2023). "In conclusion, DTPA-700DX-MB binds to FAP-expressing cells and targets PDAC299 tumours in mice with good signal-to-background ratios." (PMID 37408254, 2023). "OMTX705, an ADC including a humanized anti-FAP antibody and the cytolytic compound TAM470, demonstrated potent tumour growth inhibition in PDX mouse models with various solid tumours, including PDAC." (PMID 37240052, 2023). "Together, these results suggest that the combination of FAP-CAR and Meso-CAR T cells treatment can also promote endogenous adaptive anti-tumor immunity." (PMID 37607999, 2023). "Binary logistic regression analysis revealed that tumor location, PCA, and FAP were independent predictors of GHA discrimination from GA." (PMID 37538113, 2023). "The results of GEPIA showed that the expression levels of CCT6A and FAP were increased in the tumor tissues of GC patients, and the expression levels of ZFP36 and TP53I3 were decreased in the tumor tissues of GC patients." (PMID 36010886, 2022). "Our work confirms and extends these observations by demonstrating the power of FAP to distinguish CMS4 from CMS1-3 (AUC = 0.91) and by providing clinical proof-of-concept for the detection of a CMS4 tumour by FAPI-PET." (PMID 35296803, 2022). "To address the low tumor retention of the FAPI series, we developed the FAP-2286 compound, based on a novel class of FAP-targeting modalities, that utilizes cyclic peptides as binding motifs." (PMID 35608703, 2022). "A further antibody-conjugate targeting FAP, FAP5-DM1, has also been shown to have an inhibitory effect on tumor progression, inducing complete regression in a PAAD xenograft model with good efficacy and tolerability." (PMID 36263225, 2022). "The search terms “ectoprotease”, “cell surface protease”, “DPP4/CD26”, “FAP/Seprase”, “APN/CD13”, “ADAM17/TACE”, “MMP/gelatinase”, “drug”, “inhibitor”, “clinical trial”, “metabolism”, “tumour”, “microenvironment” were employed for this purpose." (PMID 35158891, 2022). "DMS functionalized with CAF-targeting anti-FAP-α antibodies (antiCAFs-DMS) can selectively inhibit Pin1 in CAFs, leading to efficacious but transient tumor growth inhibition." (PMID 35879297, 2022). "Levels of additional CAF markers such as fibroblast activation protein (FAP) in MH6419 tumours and PDGFRβ in B16F10 tumours were also significantly reduced in Atf4Δ/Δ mice." (PMID 35654839, 2022). "FAPα is highly expressed in CAFs and is known to promote a protumoral TME through remodeling of the tumor stroma." (PMID 35986369, 2022). "FAPα promoted CXCL5 secretion in HSCs, which activated CXCR2 to promote the epithelial-mesenchymal transition of tumor cells and the recruitment of myeloid-derived suppressor cells." (PMID 35951441, 2022). "sc-CAFs-NFs analysis revealed a significant increase in CAFs expression of 3 exiting marker genes (FAP, COL11A1 and POSTN) and 2 newly proposed markers (COL6A3 and MFAP2) in all tumor types we studied." (PMID 36263012, 2022). "In contrast to the fibroblasts from adjacent tissues of the same OSSC patients, a higher expression of FAP and α‐SMA was detected in fibroblasts from tumor tissues, whereas the epithelial cell marker PanCK was only expressed in tumor cells." (PMID 33657265, 2022). "The authors observed T-cell responses towards FAP and TRP2, enhanced CD8+ T-cell infiltration and antigen spreading, leading to potent anti-tumour activity." (PMID 35814453, 2022). "In order to gain more insight into the different tumor retention time of both molecules, AF488-labeled FAP-2286 and FAPI-46 were synthesized for studying cellular internalization, localization, and retention by live cell fluorescence microscopy." (PMID 35608703, 2022).
tumor (continued). "As tumor STF2 (CSPG4-high) and STF3 (FAP-high) represent distinct CAF populations, we then performed a coexpression correlation analysis between INHBA expression and the respective cluster markers." (PMID 34642171, 2022). "COL4A1, COL6A3, FAP, and LY6E were up-regulated in the tumor group in the training set, whereas ABCA8, MAMDC2, TMEM100, and TMEM266 were down-regulated." (PMID 36685898, 2022). "At 0.5 h after administration of 68Ga-FAP-2286 and 68Ga-FAPI-46, tumor uptake was 9.8 and 9.3 %ID/g, respectively." (PMID 35608703, 2022). "On similar lines, Hou and colleagues (2019) designed a nanoparticle (HA@DSP-pep-DSP) based on the FAP cleavable peptide DATGPA, from which dox loaded poly (amidoamine) particles were released (mediated by glutathione) and accumulated in the tumour stroma." (PMID 35814453, 2022). "In ILC, the expression of fibroblast-activation protein alpha and fibroblast-specific protein 1/S100A4 was higher in both the tumor and stromal cells than in NST." (PMID 35205688, 2022). "Based on their selective and strong binding to FAP, a multitude of radiolabeled FAP inhibitors (FAPI) have been generated and are now widely used in experimental tumour diagnosis." (PMID 35158891, 2022). "Given the avidity of FAP for tumors as demonstrated by the remarkable success of FAP imaging agents, newer compounds including FAPI-42 are being developed to increase tumor retention time." (PMID 35626272, 2022). "In this model, exosomes increase FAPα levels and activate YAP1 signaling to promote CAF-mediated effects, including fibrosis and tumor growth, while concurrently inducing an immunosuppressive TME that benefits NPC progression." (PMID 35986369, 2022). "On the other hand, in mice models, by subtracting the FAP-positive CAFs and by inhibiting cytokines, such as SDF-1, the resulting immune control of tumor growth and the efficacy of immunotherapy are accelerated in pancreatic cancer." (PMID 36139552, 2022). "As the primary source of CCL2, FAP+ CAFs undergo crosstalk with circulating MDSCs expressing the CCL2 receptor (CCR2), thereby forming a CCL2–CCR2 axis that plays a role in mediating tumor promotion." (PMID 36263225, 2022). "Tumor cells express prostate-specific membrane antigen (PSMA) and fibroblast activation protein (FAP) is expressed across the tumor microenvironment." (PMID 36295845, 2022). "For example, an oral DNA vaccine targeting FAP has successfully demonstrated its ability to induce CD8+ T cell-mediated killing of CAF and to suppress primary tumor cell growth and metastasis of colon and breast murine carcinoma." (PMID 36338519, 2022). "Although different from tissue absorption and clearance with [68Ga]Ga-DOTA-FAPI-04, the 11C-labeled FAP inhibitors 11C-RJ1101 and 11C-RJ1102 experience similar tumor uptake and longer tumor retention times." (PMID 35991604, 2022). "A combined application of FAP-CAR T and tumor-antigen CAR T cells resulted in anti-tumor activity superior to treatment with either CAR T alone." (PMID 35741103, 2022). "FAP-specific CAR-T cells deplete most FAP+ cells, including CAFs, and restrict tumor stroma generation, resulting in the improved uptake and anti-tumor effects of chemotherapeutic drugs." (PMID 36010899, 2022). "Statistically significant antitumor activity was observed with tumor growth inhibition (TGI) of 111% and 113% (P < 0.05) in mice treated with 30 or 60 MBq 177Lu-FAP-2286, respectively, relative to the vehicle-treated group." (PMID 35608703, 2022). "Since we elucidated that FAP expression is associated with poor prognosis in patients with EC14, we applied NIR-PIT technology to establish NIR-PIT targeting FAP, a specific CAF marker, and successfully revealed its effect on tumor regression." (PMID 36418422, 2022). "FAPI can specifically bind with FAP, and thus, its use in PET/CT imaging can allow the detection of FAP in the tumor microenvironment, providing insight into the biological characteristics of tumors." (PMID 34870727, 2022).
tumor (continued). "To verify how the effect of GDF10 on the transformation of CAF and tumor cell growth, we determined the expression of α‐SMA and FAP in CAF transfected with si‐GDF10 by qPCR." (PMID 33657265, 2022). "FAP expression on NB cells and myeloid-derived suppressor cells (MDCS) in tumor tissue was identified." (PMID 36230765, 2022). "To further assess the spatial organization of FAP+ fibroblasts and SPP1+ macrophages, we performed spatial transcriptomics (ST) with tumor tissue sections from four CRC patients." (PMID 35365629, 2022). "QCP01 and QCP02 were applied in tumor transplantation models with higher tumor and normal organ uptake than FAPI-02 and FAPI-04, indicating that QCP01 and QCP02 have high affinity for FAP." (PMID 35692767, 2022). "Indeed, it has been found that depletion of FAP+ cells has the effect of delaying subcutaneous tumor growth and contributes to the development of a more immunogenic environment, thereby indicating that FAP-expressing stromal cells could play important roles as immunomodulators." (PMID 36263225, 2022). "The limitation of this study is the mouse models from cancer cell-derived xenografts (CDXs), which cannot express both FAP and PSMA receptors in one tumor-bearing model." (PMID 35337180, 2022). "We observed higher expression of both FAP and INHBA in tumor fibroblasts compared with normal (P < 0.05), and within tumor fibroblasts there was a strong correlation between FAP and INHBA coexpression levels (R = 0.92, P < 0.0001)." (PMID 34642171, 2022). "Amongst case versus control primary CRC, there was a significantly higher proportion of POSTN tumour, POSTN stroma and FAP tumour positivity in the case group." (PMID 34874125, 2022). "CXCL12, produced by FAP+CAFs in the TME binds to its receptor CXCR4, expressed by T cells, thereby trapping TIL in the tumour stroma and restricting their access to tumour areas containing cancer cells." (PMID 35479076, 2022). "The specific recognition of CMS4 by FAPI-PET is based on FAP expression, predominantly in myofibroblasts, a cell type that is highly enriched in CMS4 tumours." (PMID 35296803, 2022). "FAP also induces inflammatory CAFs by STAT3 activation leading to increased expression of CCL2, which promotes the tumor recruitment of myeloid-derived suppressor cells (MDSCs) and immunosuppression." (PMID 35222418, 2022). "FAP is a type II transmembrane serine protease, and [68Ga]Ga-DOTA-FAPI-04 is used for imaging tumor stromal." (PMID 35785188, 2022). "In particular, FAP-specific CAR T cells have been used to reduce tumor-cell growth, with minimal off-tumor toxicity." (PMID 34302116, 2022). "FAP can also induce the drug resistance of cell lines, thereby inhibiting the anti-tumor ability of T cells in GC TME, and can also promote the anti-tumor effect of ICIs in GC patients." (PMID 36010886, 2022). "Next, we verified that the fibroblasts around tumor buds showed a high expression of α-SMA and CD90 but a low expression of FAP (α-SMAhigh CD90high FAPlow)." (PMID 35241150, 2022). "We observed that BCCs-dependent TGF-beta pathway activation in BFs led to increased FAP expression, thereby corroborating the fact that CAF-S1 and pCAFs are predominantly detected close to epithelial tumor cells in patients." (PMID 36085201, 2022). "Given that tumor-derived CXCL5 promotes tumor cell EMT and MDSC recruitment by activating CXCR2, we proposed that HSC-derived FAPα promoted tumor cell EMT and MDSC recruitment through the CXCL5/CXCR2 axis." (PMID 35951441, 2022). "CMS4 probabilities, calculated for each individual tumour region by applying the random forest CMS classifier, show a strong correlation with FAP expression in those same regions." (PMID 35296803, 2022). "In the subcutaneous xenograft tumor model, we found that the stromal activation markers of CAFs such as a-SMA and FAP in tissues were significantly lower in BAPN group via IF staining." (PMID 35966586, 2022).
tumor (continued). "Compared with the monomers, the dual-targeting heterodimeric radiotracers showed increased tumor uptake and retention in PSMA and FAP-positive tumors." (PMID 35337180, 2022). "Previously, we found that [177Lu]lutetium sesquioxide nanoparticles functionalized with FAP and PSMA inhibitor ligands (iFAP and iPSMA) ([177Lu]Lu−iFAP/iPSMA) prevent HCT116 tumor progression in mice." (PMID 36500804, 2022). "Different subtypes of CAFs display specific functions in tumor pathogenesis and various CAF markers suggest potential treatment targets, such as FAP and GPR77." (PMID 35681617, 2022). "Significant inhibition of cell proliferation in vitro and in tumors was observed due to the accumulation of nanoparticles in the fibroblasts (FAP+) and neovasculature (PSMA+) of the tumor microenvironment." (PMID 36500804, 2022). "With FAP‐CAR‐T cells, tumour vasculature density is greatly reduced and the growth of desmoplastic cancer is retained." (PMID 36495108, 2022). "To exploit the favorable properties of heterodimers, we designed and developed bi-specific heterodimeric radiotracers targeting both FAP and αvβ3 for [68Ga]Ga-based PET imaging in multiple tumor types." (PMID 36276644, 2022). "As FAP is only expressed at insignificant levels in adult normal tissue, FAPI provides a highly specific tumor-marker for many epithelial cancers." (PMID 36428657, 2022). "Cancer-associated fibroblasts (CAF) express more biomarkers than normal fibroblasts do, including FAP and αSMA, which have been used as biomarkers to isolate CAF populations from the tumor tissue." (PMID 36232893, 2022). "The expression of FAP, α-SMA, and Vimentin was more strongly correlated with NFYB, and these markers were closely related to tumor invasion and metastasis." (PMID 36152055, 2022). "FAP+-CAFs were isolated by digestion of murine hepatoma tumor tissues and found to be an important source of the chemokine CCL2, which mediates tumor inflammation and immunosuppression." (PMID 34771577, 2021). "CXC-chemokine ligand 12 (CXCL12) is another immune-modulating factor that is expressed by FAP+ CAF cells and is responsible for tumor cell survival and T cell compartmentalization within the TME in a lung cancer mouse model." (PMID 33806802, 2021). "Adoptive transfer of FAP-specific CAR T cells reduces FAP-positive stromal cells and concomitantly decreases tumor xenograft growth." (PMID 33572223, 2021). "In the case of the other three markers, FAPα, CD26 and PDGFRα, these showed divergent dynamics across time in the two tumour types." (PMID 34016130, 2021). "Here, TGFβ1 increased FAP expression in CD90+CD73+ peritumoral cells and FAP+ cells were observed adjacent to and surrounding tumour epithelium." (PMID 34740105, 2021). "In contrast to 18F-FDG, targeting FAP with the novel tracer, 68Ga-FAPI-04, has been shown to be suitable for marking CAFs and tumor imaging in preclinical GC models." (PMID 35155199, 2021). "The four αFAP–TNFL bifunctional reagents were studied in the 3D tumor spheroid model with MCF-7 and HT-1080/FAP cells blended in a 1:1 ratio." (PMID 34484225, 2021). "Meanwhile, Feig and coworkers showed that depletion of FAP-positive CAFs, in PDAC-bearing mice, enabled the immune control of tumour growth and the antitumour activities of α-CTLA-4 and PDL1 antibodies." (PMID 33806468, 2021). "A novel PET tracer based upon quinoline FAP-specific inhibitors (FAPI) has recently been developed and used to target FAP and to visualize the tumor stroma." (PMID 34604078, 2021). "Moreover, anti-tumor necrosis factor alpha and anti-IFNγ treatment counteracted the reduced tumor growth that was observed after the decrease in FAP+ cells, suggesting that FAP may inhibit the production of tumor necrosis factor alpha and IFNγ or weaken the cellular response to these cytokines." (PMID 34490078, 2021).
tumor (continued). "The combination of FAP+ CAF and EPH receptor A2 (EphA2)+ targeting resulted in complete tumor remission, which suggests a crucial supplemental role of CAF-targeting strategies along with conventional cancer therapies." (PMID 33806802, 2021). "The preliminary human applications using the early FAP inhibitor, namely FAPI02, demonstrated high tumor specificity but declining uptake over time." (PMID 34858834, 2021). "One of the advantages of targeting FAP-expressing CAFs is the absence of FAP expression in quiescent fibroblasts, leading to a controlled targetability of diagnostic and therapeutic compounds to the malignant tumor stromal area using radiolabeled FAP-based ligands." (PMID 34681246, 2021). "Although the Standardized Uptake Values (SUVs) are similar between FAP-targeted tracers and [18F]-FDG, the tumor-to-background ratios are considerably higher due to a lower accumulation in non-target tissues." (PMID 34830898, 2021). "Nevertheless, FAP+ CAFs depletion disrupted a CAF/cancer cell dialog through CXCR4/CXCL12 pathway inhibition, thereby restoring immune control of tumor growth." (PMID 34298680, 2021). "Preclinical studies in cells expressing human and murine FAP and CD26 resulted in an increased half-life of 3.0 h for [177Lu]Lu-FAPi-04, versus 1.7 h for [177Lu]Lu-FAPi-02 in the tumor." (PMID 34959613, 2021). "Analysing 128 murine tumours, we identified 5–6 main CAF populations and numerous minor ones based on the analysis of αSMA, FAPα, PDGFRα, PDGFRβ, CD26, and PDPN." (PMID 34016130, 2021). "Preclinical studies have verified the promising effects of eliminating FAP-positive CAFs to increase the recruitments of anti-tumor CD8 + T cells into tumor stroma, hence rekindling the anti-tumor immunity and suppressing tumor progression." (PMID 34670584, 2021). "designed FAP-CAR T cells to target fibroblasts in the tumor microenvironment (TME), leading to reduce the number of tumor fibroblasts and inhibition of tumor growth." (PMID 33522929, 2021). "They adopted fibroblast activation protein (FAP), which is expressed in the tumor stroma as a TAA, and evaluated the combination therapy of FAP-4-1BBL and anti-CEA/CD3 T-BsAb." (PMID 34832954, 2021). "Immunohistochemistry demonstrated that proportion of CAF accumulated in tumours was remarkably downregulated following the treatment of MMF‐LA@DSPE‐PEG, as the expression levels of α‐SMA, FAP and collagen IV were significantly decreased." (PMID 33713546, 2021). "Targeting the CXCL12-CXCR4 axis by treatment with a specific CXCR4 inhibitor AMD3100, also known as Plerixafor, reverses FAP-positive CAF-mediated immunosuppression, infiltration of CD8+ T cells into the tumor." (PMID 33572223, 2021). "Several radiolabeled FAP inhibitors (FAPI) targeting FAP expression in CAFs and characterized by rapid renal clearance and high tumor-to-background uptake ratio (TBR) have been developed to allow early cancer detection through PET imaging." (PMID 34681850, 2021). "In a preclinical mouse model, the combination of bispecific molecules targeting CD3/CEA and CD137L/FAP showed synergistic anti-tumor effects and this was accompanied by an increase of more CD8+ T cells in tumor than with a CD3/CEA bispecific molecule only." (PMID 34064598, 2021). "RG7386 also inhibited tumor growth in a TNBC xenograft model generated by co-injection of MDA-MB-231 and fibroblasts, NIH3T3, only in the presence of FAP expressing stroma." (PMID 34944738, 2021). "The use of tumour-specific tracers, targeting, for example, ER (e.g. [18F]FES), HER2 (e.g. [68Ga]ABY-025), PARP (e.g. [18F]SuPAR), FAP (e.g. [68Ga]FAPI) or GRPR (e.g. [68Ga]RM2) are likely to further improve the diagnostic accuracy of FAR." (PMID 33738563, 2021). "FAP+CAFs were the main source of CCL2, which facilitated the recruitment of myeloid-derived suppressor cells (MDSCs) to the tumor and promoted immunosuppression in a CCR2 dependent manner." (PMID 34336660, 2021).